CXCR4 (C-X-C motif chemokine receptor 4)
Diseases named in the same sentence as CXCR4 in open-access papers (continued):
Sharing a sentence is not in itself a finding about the gene and the disease.
glioma (continued). "Even though 64Cu-complexed Plerixafor AMD3465 showed high tumor and liver uptake in vivo, the additional positive charge from radiometal might prevent it from crossing BBB and target CXCR4-positive gliomas." (PMID 32239371, 2020). "Glioma-initiating cells were protected from RT-induced cell death by this increase in TGFβ production, which promoted an effective DNA damage response and self-renewal via C-X-C chemokine receptor type 4 (CXCR4) and NOTCH1." (PMID 33050580, 2020). "Anti-miR-21 or sh-CXCR4 alone was able to significantly limit the invasiveness of glioma cells." (PMID 33123586, 2020). "Moreover, CXCL12 and its receptor CXCR4 have been shown to promote VEGF production mediated by glioma stem cells and tumor angiogenesis via PI3K/AKT signaling." (PMID 32456359, 2020). "As CXCR4 is highly expressed on GICs and glioma tumor sites, meanwhile, the activation of CXCR4 induces the receptor‐stimulated macropinocytosis pathway in GICs, this CXCR4 receptor‐stimulated lipoprotein‐like nanoparticle (SLNP) achieves efficient accumulation in GICs in vitro and in vivo." (PMID 32154087, 2020). "Administration of either CXCR4 neutralizing antibody or CXCR4 siRNA impairs the enhanced glioma malignancy (proliferation, angiogenesis, invasion, metastasis, and postchemotherapy and postradiotherapy recurrence) and increases median survival in vivo glioma models." (PMID 33123586, 2020). "Studies have revealed that targeting the CXCR4 pathway may provide a therapeutic approach against glioma." (PMID 32194542, 2020). "These strong associations suggest that EZH2 and CXCR4 overexpression promotes tumor progression and that EZH2 and CXCR4 could possibly be used as biomarkers for a more aggressive phenotype of gliomas." (PMID 32635336, 2020). "Moreover, the protein expression of CXCR4 increased with the tumor grade and was significantly higher in gliomas of grade III and IV than in gliomas of grade II." (PMID 32456359, 2020). "However, 76Br-HZ2701 was unable to successfully image a CXCR4-expressing intracranial glioma (U87-CXCR4) or a CXCR4-expressing intracranial PCNSL (PCNSL-15) following i.v. or spinal-CSF injection." (PMID 32239371, 2020). "The growth of glioma tumor was significantly suppressed in anti-miR-21 or sh-CXCR4 treatment alone groups compared to negative control, while the anti-miR-21 + sh-CXCR4 treatment obviously reduced the tumor growth compared to the anti-miR-21 or sh-CXCR4 group." (PMID 33123586, 2020). "It was demonstrated that CXCR4 is a major chemokine receptor on glioma cells." (PMID 32456359, 2020). "In this study, we report that EZH2 and CXCR4 were overexpressed in glioma patients." (PMID 32635336, 2020). "It was shown that pattern of CXCL12 and CXCR4 expression may be also a predictive factor of glioma recurrence after its total resection." (PMID 32456359, 2020). "Targeting CXCL12/CXCR4 autocrine/paracrine loop could inhibit the survival and proliferation of glioma stem cells and drive the migration of GSCs to neurogenic zone." (PMID 31382985, 2019). "Therefore, we also measured the expression level of CXCR4 in serum EVs from glioma patients at different stages." (PMID 31410219, 2019). "Furthermore, Notch1, Hes1 and CXCR4 expressing cells colocalized with or adjacent to the Nestin expressing glioma cells." (PMID 31382985, 2019). "Interestingly, these CXCR4 positive glioma cell, usually expressed Notch1 both and dispersed in the periphery of the sphere." (PMID 31382985, 2019). "shRNA-mediated knockdown of CXCR4 in vivo also proved that CXCR4 could increase glioma perivascular invasion and reduce radiation-induced apoptosis." (PMID 30233327, 2018). "The SDF-1/CXCR4 axis may also contribute to the migration of MSCs into the brain and towards glioma tissue in irradiated animals." (PMID 29734748, 2018).
glioma (continued). "This might highlight another difference between the early and late stages of tumor growth, as autocrine SDF1/CXCR4 signaling has been shown to be involved in proliferation of various glioma cell lines." (PMID 29465400, 2018). "All these factors suggest a positive role of CXCR4 in glioma progression." (PMID 30233327, 2018). "Hence, interstitial flow is indeed able to stimulate invasion of glioma cells in vivo mediated at least in part through CXCR4 signaling." (PMID 30451884, 2018). "On the other hand, CXCR4 activation triggered VEGF-dependent neoangiogenesis in glioma and breast cancer cells, suggesting that CXCL12 may synergize with other pro-angiogenic factors to induce the formation of new blood vessels." (PMID 29240722, 2017). "Therefore, nestin, ABCG2 and CXCR4 are included as the phenotype markers for identifying glioma stem cells." (PMID 28615716, 2017). "Experimental and clinical evidence have indicated that the CXCL12/CXCR4 axis promotes new blood vessel formation in diverse types of malignancies, including breast, ovarian, prostate, hepatic, gastric, colorectal cancer, and glioma." (PMID 29240722, 2017). "After verifying the correlation of HIF1α and MIF with CXCR4 in gliomas, we further explored whether hypoxia-induced high co-expression of MIF and CXCR4 was correlated with the formation of VMs." (PMID 29113309, 2017). "In another study, dense intra-tumoral microvessels have been observed near CD133+ glioma CSCs that co-express the CXCR4, and one study has shown that CXCR4+ subpopulations of CD133+ pancreatic CSCs can evade primary tumors and disseminate into the blood stream." (PMID 28757546, 2017). "Finally, to evaluate the clinical significance of MIF, CXCR4 and VMs in glioma, overall survival was analyzed by stratifying patients according to the immunochemistry score for MIF and CXCR4 or VM-positive." (PMID 29113309, 2017). "Furthermore, a closely positive relationship between VM formation and high co-expression of MIF and CXCR4 was revealed within hypoxic regions of gliomas." (PMID 29113309, 2017). "If resistance to cancer therapies is dependent upon localization of tumor cells to the perivascular space, we asked if CXCR4-knock down glioma cells, which lose their ability to migrate into perivascular space would be more sensitive to radiation-mediated killing." (PMID 27863376, 2016). "To test this hypothesis, we examined the interaction of genetically modified low CXCR4 expressing GL26-Cit-sh2CXCR4 cells versus control implanted gliomas with the existing vasculature at the tumor border." (PMID 27863376, 2016). "Thus, we anticipated that CXCR4-knockdown mouse glioma cells (GL26-Cit-Sh2CXCR4) will be less invasive due to reduced association with brain vessels." (PMID 27863376, 2016). "Our radiation experiment confirmed this hypothesis by showing increased apoptosis in glioma tumors knocked down for CXCR4 and irradiated." (PMID 27863376, 2016). "Although, there are reports about targeting CXCR4 in combination with current treatment regimens available for GBM patientsnone have utilized the shRNA mediated inhibition of the CXCR4 gene on glioma cells in order to understand its in-vivo role in glioma's perivascular invasion." (PMID 27863376, 2016). "Thus, our experiments suggest that CXCR4 has a role in downregulating apoptosis, maintaining glioma cell viability, and thus reducing survival of irradiated glioma tumors." (PMID 27863376, 2016). "Migration of CXCR4 knockdown mouse glioma GL26-Cit cells was significantly reduced." (PMID 27863376, 2016).
glioma (continued). "However, we detected a higher number of iNOS+/Arg-1+ in peptide R-treated gliomas, further supporting the ability of the novel CXCR4 antagonist to modulate the reactivity of GAMs." (PMID 27015814, 2016). "Thus shRNA mediated selective knock down of CXCR4 demonstrates that CXCR4 plays critical role in chemotactic migration of GBM cells towards brain endothelial cells and downregulation of CXCR4 has direct impact on the ability of glioma cell migration." (PMID 27863376, 2016). "The current series of experiments tested hypothesis that the chemotactic migration of tumor cells in perivascular space and their resistance to cancer therapies depends on the expression of CXCR4 on glioma." (PMID 27863376, 2016). "Recent studies indicate that glioma cells have increased expression of CXCR4." (PMID 27863376, 2016). "Additionally, IFF has been shown to enhance glioma invasion through CXCR4/CXCL12-dependent autologous chemotaxis." (PMID 26560447, 2015). "Furthermore, TMP effectively inhibits the cell viability and migration of cultured C6 glioma cells by down-regulating CXCR4 expression." (PMID 26275042, 2015). "Our previous studies have demonstrated that TMP might inhibit cornea neovascularization, attenuate pulmonary fibrosis and suppress glioma cell behavior by regulating the SDF-1/CXCR4 axis." (PMID 26275042, 2015). "Moreover, in the present study, we demonstrated that the decrease in CXCR4 expression induced through TMP is 3.94-fold greater than the decrease in VEGF expression in C6 glioma cells." (PMID 24505417, 2014). "In summary, the studies described here show that CXCR7 is a hypoxia-responsive mediator of SDF-1α-induced glioma cell migration and support the development of therapeutic agents for the pharmacological inhibition of CXCR4 and CXCR7 to control glioma cell migration." (PMID 23865743, 2013). "Furthermore, overexpression of CXCR4, a chemokine receptor known to mediate glioma cells invasiveness, has been correlated with increased T2." (PMID 23865826, 2013). "Antagonism of CXCR4 can inhibit human glioma growth, invasion, and pro-MMP2 activation." (PMID 23555768, 2013). "We have previously shown that CXCR4-positive glioma cells increase their migration towards SDF-1α." (PMID 23865743, 2013). "Other authors found that CXCL12 might stimulate cell migration, cell growth, and invasion of ovarian cancer cells, and that CXCR4 was found to be expressed on the majority of glioma cell lines studied and on patients' tissue samples." (PMID 18781150, 2008). "Notably, the group with high Endothelial Score and high CXCR4 expression showed the worst prognosis compared to the other three groups, indicating that the Endothelial Score-CXCR4 axis could serve as a prognostic marker in gliomas." (PMID 41041071, 2025). "Besides, hsa-miR-224-5p could downregulate CXCR4 level in glioma cells, resulting in the inhibited glioma development." (PMID 35059468, 2022). "Moreover, rodent models suggest efficacy of CXCR4 targeting in the treatment of stroke and glioma." (PMID 34054860, 2021). "CXCR4 inhibition using plerixafor was therefore proposed in combination with bevacizumab (anti-vascular endothelial growth factor monoclonal antibody) for diminishing resistance to this anti-angiogenic therapy and has thus far proven safe in patients with high-grade gliomas." (PMID 35008294, 2021). "Moreover, TNFα has been reported to increase CXCR4 expression in glioma cells." (PMID 34764346, 2021). "However, the authors utilized CXCR4 expression within gliomas to target VEGF mediated angiogenesis." (PMID 34203660, 2021). "Moreover, the dysregulation of CXCL12/CXCR4 signaling induces aberrant astrocyte proliferation, which could also contribute to glioma progression." (PMID 34084145, 2021). "Thus, our data reported that anti-miR-21 + sh-CXCR4 could diminish growth of glioma xenograft in vivo." (PMID 33123586, 2020).
glioma (continued). "In addition, CD133+ and Nestin+ glioma stem-like cells could also regulate SDF-1α and CXCR4, which subsequently promote leukocyte migration and glioma progression." (PMID 32725165, 2020). "In our study, we confirmed that the miR-21 and CXCR4 expressions were significantly upregulated in glioma tissues compared to normal tissues and cells, which suggested that miR-21 and CXCR4 might play important roles in mediating malignant glioma aggressiveness, as well as the tumorigenicity." (PMID 33123586, 2020). "As the CXCR4 positive glioma initiating cells co-expressed with Notch1 usually dispersed in the periphery of the tumorsphere, we put forward the hypothesis that CXCR4 might exert a crucial role in the Notch1 signaling mediated stem maintenance and migration of GICs." (PMID 31382985, 2019). "Other molecular pathways that have been described to promote radiation-induced invasion in glioma include melanoma differentiation-associated gene 9 (MDA-9), the transcription factor signal transducer and activator of transcription 3 (STAT3), and the chemokine receptor CXCR4." (PMID 30463322, 2018). "Moreover, in gliomas characterized by high vasculogenic potential, the incorporation of EPCs into blood vessels was associated with CXCL12 secretion, whereas the CXCR4 antagonist AMD3100 abrogated the ability of CXCL12 to trigger EPC incorporation into the tumor vasculature." (PMID 29240722, 2017). "Additionally, genetic down regulation of CXCR4 in mouse glioma GL26-Cit cells inhibits their in-vitro migration towards MBVE cells; in an in-vivo intracranial mouse model, these cells display reduced tumor growth and perivascular invasion, leading to increased survival." (PMID 27863376, 2016). "Therefore, we wished to test whether CXCR4 suppression would improve the median survival of mice implanted with GL26-Cit-sh2CXCR4 glioma cells." (PMID 27863376, 2016). "Thus, CXCR4 knockdown in glioma cells confirmed our hypothesis that glioma invasion of the perivascular space at the tumor border is dependent on CXCR4 expression on glioma cells." (PMID 27863376, 2016). "Since Nordy can inhibit angiogenesis by regulating CXCR4-mediated production of VEGF by glioma cells, we attempted to confirm whether the combination of Nordy and the VEGF receptor tyrosine kinase inhibitor could enhance suppression of angiogenesis that was induced by GSCs." (PMID 24454929, 2014). "The TMP-mediated down-regulation of CXCR4 in cerebral neurocytes inhibits somatic Ca2+ increase, decreases glutamate release from glial cells, and effectively inhibits the viability and migration of cultured C6 glioma cells, which induces neural protection and the suppression of C6 gliomas." (PMID 24505417, 2014). "Glioma cell lines (U87, SHG-44, and CHG-5) and human primary glioma specimens express higher levels of CXCL-12 and CXCR4 mRNA." (PMID 40727443, 2025). "TMP disrupts CXCR4/SDF‐1 signaling pathway, in glioma C6 cells inhibiting glioma cell migration and angiogenesis." (PMID 40014265, 2025). "The MIF signals sent by glioma cells (Clusters C1, C2 and C4) were mainly received by TAMs (Cluster C0) via receptors CD74 and CXCR4, and by lymphocytes (Cluster C6) via CD74, CXCR4 and CD44." (PMID 38515213, 2024). "In these immunostimulators genes, CXCR4, CXCL12 belonged to Chemokines and chemokine receptors, were also positively correlated with IGFBP5 expression in glioma." (PMID 38164271, 2024). "Our analysis identifies critical ligand-receptor pairs between TAMs and glioma cells that promote tumor progression, such as MIF-CD74/CXCR4, THY1-ITGAX/ITGB2, and ANGPTL2-TLR4." (PMID 38515213, 2024). "The CXCL12/CXCR4 signaling pathway is activated in GBM and is critical for sustained glioma invasion, enhanced angiogenesis, and glioma stem cell migration." (PMID 37626511, 2023).
glioma (continued). "The tracer showed radiochemical stability, and high affinity for CXCR4 expressing malignancies and was proposed for SPECT/computed tomography (CT) imaging of glioma and of different cancers with CXCR4 expression." (PMID 36986728, 2023). "A 2006 study of the U251 glioma cell line revealed that VEGF increases expression of both SDF-1 and CXCR4 mRNA, thus effectively improving metastatic capabilities." (PMID 37153567, 2023). "This distinction highlights the complex role of the trio CXCL12/CXCR4/CXCR7 in the bidirectional interaction between astrocytes and glioma cells." (PMID 38293652, 2023). "In this regard, the novel-designed peptide NT21MP of viral macrophage inflammatory protein II (vMIP-II) targeted CXCR4 and inhibited SDF-1α activation in a vitro model of glioma." (PMID 36980182, 2023). "In the glioma, LRRC4, an onco-suppressive gene, inhibited CXCR4-induced cell invasiveness by reducing ERK1/2 and Akt signaling." (PMID 36103228, 2022). "The protein level of CXCR4 was also detected in NHA and glioma cell lines, consistent with the qPCR results." (PMID 35059468, 2022). "Among them, one gene (CXCR5) was downregulated while five other genes (CXCR1, CXCR2, CXCR3, CXCR4, and ACKR3) were enriched in glioma compared with normal brain tissues." (PMID 35571062, 2022). "We found that the following neutrophil chemokines—MMP9, CCL2, CCL5, CXCR4, CXCR2, CCL23, and IL8 (p = 0.07)—were enriched in TERTmut gliomas (t-test, p < 0.05)." (PMID 33996815, 2021). "An increased expression of CXCR4 mRNA and CXCL-12 levels has been observed in human primary glioma specimens and glioma cell lines (U87, SHG-44, and CHG-5)." (PMID 34439380, 2021). "Hypoxic peri-arteriolar glioma stem cell niches exist in human glioblastoma samples, with the SDF-1α/CXCR4 signaling axis and osteopontin/CD44 interactions being involved in the homing of glioma stem cells in their niches and their maintenance." (PMID 34771577, 2021). "In TCGA database, GBM tissue had higher CXCR1, CXCR2, CXCR4, and CCR5 expression compared with WHO grade II and III glioma." (PMID 34638384, 2021). "There is a vast number of additional CXCR4 inhibitors including CPZ1344, AMD3465 and Peptide R that reduced tumor growth and inhibited migration and angiogenesis of glioma cells." (PMID 34203660, 2021). "The cross-talk between Notch1 signaling and CXCL12/CXCR4 system contributes to the progression and recurrence of GBM by promoting the self-renewal and invasion of glioma stem cells." (PMID 33552592, 2021). "For signaling pathways genes, the expression of CXCR4, BIRC5, CTNNB1, FZD4, and MET were significantly increased in high-grade gliomas." (PMID 32154177, 2020). "Another chemokine that plays a crucial role in the growth and proliferation of gliomas is CXCL12, whose activity is mediated through conventional chemokine receptor CXCR4." (PMID 32456359, 2020). "Using immunohistochemical techniques in glioma tissues obtained in total tumor resection, it was demonstrated that CXCL12 was expressed mainly in vascular endothelial cells, while CXCR4 immunostaining was observed mainly in tumor cells." (PMID 32456359, 2020). "Different glioma cell lines and PCNSL xenografts expressed different amounts of CXCR4 (green immunostain), providing a range of expression levels for testing the CXCR4 imaging efficacy of the radiolabeled cyclam derivatives in these animal models." (PMID 32239371, 2020). "Chemokine (C-X-C motif) ligand 12 (CXCL12) and its receptors CXCR4 and CXCR7, which are stored in or attached to the ECM, are extremely important in forming a more invasive and resistant phenotype of glioma." (PMID 31611911, 2019). "Both CXCR4 and CD44 are highly upregulated in glioma, which further enhances the importance of studying flow in conjunction with these cancers." (PMID 31632905, 2019). "(c) The expression of CXCR4 and CXCL12 in high grade glioma tissues through immunohistochemistry analysis." (PMID 31382985, 2019).